NCF2 (neutrophil cytosolic factor 2)
Diseases named in the same sentence as NCF2 in open-access papers (continued):
Sharing a sentence is not in itself a finding about the gene and the disease.
migraine with aura (1 paper, 2025). A migraine disorder characterized by episodes that are preceded by focal neurological symptoms. "The target NCF2, associated with Agents acting on the renin‐angiotensin system, is linked to a reduced risk of migraine with aura (OR (95% CI) = 0.674 (0.538−0.843), PSMR = 5.60×10−4)." (PMID 41261954, 2025). "At the brain‐tissue level, we further validated hub gene associations: in migraine, SERPINC1, ZKSCAN8P1, C12orf76, and PAM were significant across brain regions; in migraine with aura, SERPINC1, ALMS1, ZKSCAN8P1, PAM, and NCF2 were significant." (PMID 41261954, 2025). "SMR and INTACT confirmed the validity of BLM, C12orf76, GPATCH4, PAM, SERPINC1 for migraine, and ALMS1, GPATCH4, NCF2, SLC12A1, ZKSCAN8P1 for migraine with aura." (PMID 41261954, 2025). "For migraine with aura, SERPINC1, ALMS1, ZKSCAN8P1, PAM, and NCF2 were significant (p < 0.05); SERPINC1 was significant in nine regions, with the most pronounced association in the Nucleus accumbens (basal ganglia) (p = 0.014)." (PMID 41261954, 2025). "The results of the SMR, colocalization, and INTACT sensitivity analyses provided further validation of BLM, C12orf76, GPATCH4, PAM, SERPINC1 as contraindicated drugs’ target genes for migraine, and ALMS1, GPATCH4, NCF2, SLC12A1, ZKSCAN8P1 for migraine with aura." (PMID 41261954, 2025).
multiple sclerosis (1 paper, 2020). A progressive autoimmune disorder affecting the central nervous system resulting in demyelination. "In multiple sclerosis, NCF2 was identified to be associated with eleven single nucleotide polymorphisms." (PMID 33553270, 2020).
ovarian carcinoma (1 paper, 2014). A malignant neoplasm originating from the surface ovarian epithelium. "The remaining genes among these down-regulated candidates have no previous association with ovarian cancer: Gpr64, Gpr126, Cybrd1, Star, Ncf2." (PMID 24672774, 2014).
prostate carcinoma (1 paper, 2023). A carcinoma that arises from epithelial cells of the prostate gland. "NCF2/p67phox, the activating subunit of NADPH oxidase, is aberrantly expressed in several genitourinary tumors with clinical significance, including ccRCC, prostate cancer, urothelial carcinoma and testicular cancer." (PMID 37612524, 2023).
renovascular hypertension (1 paper, 2013). High blood pressure secondary to renal artery stenosis. "We found that the development of renovascular hypertension in RAS mice was associated with a rapid induction of Ncf1 and Ncf2, which encode the NADPH oxidase subunits p47phox and p67phox, respectively." (PMID 24025423, 2013).
Salmonella Infections (1 paper, 2022). Infections with bacteria of the genus SALMONELLA. "Another mutation previously linked to STm susceptibility is in Ncf2, although it is not as detrimental to murine survival after Salmonella infection as the Slc11a1 mutation." (PMID 35417454, 2022). "Furthermore, despite having susceptible alleles in both Slc11a1 and Ncf2 that are linked to early death from Salmonella infection, CC045/GeniUnc mice were able to survive 7 days with a high bacterial load and exhibited tolerance to systemic Salmonella infection." (PMID 35417454, 2022).
sarcopenia (1 paper, 2022). Progressive decline in muscle mass due to aging which results in decreased functional capacity of muscles. "The eQTL analysis for muscle mass using GTEx datasets showed that RPS10, NUDT3, NCF2, SMG7, and ARPC5 were differentially expressed in the muscle tissue for sarcopenia." (PMID 35241739, 2022).
silicosis (1 paper, 2022). Silicosis is a respiratory disease caused by breathing in (inhaling) silica dust. "In the present study, lungs of rat model of silicosis showed increased phagocyte NADPH oxidase activity with upregulated five structural components NOX2 (CYBB), p22phox (CYBA), p47phox (NCF1), p67phox (NCF2) and p40phox (NCF4)." (PMID 34991559, 2022).
squamous cervical cancer (1 paper, 2024). "The expression of NCF2 is increased in squamous cervical cancer." (PMID 38540020, 2024).
temporal lobe epilepsy (1 paper, 2024). A localization-related (focal) form of epilepsy characterized by recurrent seizures that arise from foci within the temporal lobe, most commonly from its mesial aspect. "Upregulation of leukocyte NCF2, RAC2 and HMOX1 expression in this study is predictive of low temporal lobe epilepsy seizure frequency, while downregulation of these genes predicts high seizure frequency." (PMID 38166692, 2024). "NCF2, RAC2 and HMOX1 activity all promote epileptogenicity through mitochondrial oxidative stress, neuronal lipid peroxidation, and neuronal and glial toxicity, all of which are consistent with the redox imbalance hypothesis of temporal lobe epilepsy." (PMID 38166692, 2024).
thyroid cancer (1 paper, 2025). "We used LASSO Cox regression to construct a model for the evaluation of thyroid cancer prognosis, and a risk model consisting of six genes (ACSL5, HSD17B11, CCL5, NCF2, PSME1, and ACTB) was subsequently developed." (PMID 40299520, 2025). "Further validation using qRT–PCR in 100 paired thyroid cancer and adjacent normal tissues revealed consistent upregulation of ACSL5 and NCF2 in tumour tissues and downregulation of HSD17B11, CCL5, and ACTB." (PMID 40299520, 2025).
viral infection (1 paper, 2017). "TNFAIP3, ULBP1 and TIAM1 were consistently down-regulated by viral infection, while CCL8, CCL11, CXCL11, NCF2, CSF3 and PRKCB were significantly up-regulated after infection." (PMID 28938587, 2017).
infection (24 papers, 2008 to 2025). The state of being infected such as from the introduction of a foreign agent such as serum, vaccine, antigenic substance or organism. "CC045 mice have mutations in both Slc11a1 and Ncf2, both typically leading to poor survival after STm infection." (PMID 35417454, 2022). "Polymorphisms in Ncf2 and Slc11a1, known to reduce survival in mice after STm infections, are located in the Chr 1 interval, and the Chr 7 association overlaps with a previously identified QTL peak called Ses2." (PMID 35417454, 2022). "We defined CC strains bearing Slc11a1 or Ncf2 mutations that unexpectedly survive acute STm infection." (PMID 35417454, 2022). "CC045, the only strain to carry both Slc11a1 and Ncf2 mutations, is particularly unusual since 4 out of 6 mice of this strain survived STm infections." (PMID 35417454, 2022). "Intervals on Chr 1 contained Slc11a1 and Ncf2, known genes that have mutations linked to poor survival after STm infection." (PMID 35417454, 2022). "This illustrates that the MOLF/Ei segment at Ity3.1 leads to reduced bacterial killing by the macrophages, supporting a role for Ncf2 in susceptibility of MOLF/Ei mice to infection." (PMID 24505352, 2014). "CC045 was also excluded, as it carries mutations in both Slc11a1 and Ncf2, yet survives infection." (PMID 35417454, 2022). "Natural variation in other genes has also been shown to play a role in differential survival after STm infection, including neutrophil cytosolic factor 2 (Ncf2) and toll-like receptor 4 (Tlr4)." (PMID 35417454, 2022). "Overall, 4 genes (ncf2, hmox1a, hampa, frrs1a) exhibited infection level-dependent up-regulation, and 2 genes (catc, sesn1a) showed infection level-dependent down-regulation among all genes in this category." (PMID 35035387, 2021). "A total of 117 cases of infection in the 100 patients were identified (100 associated with CYBB, 10 with CYBA, 3 with NCF1 and 1 with NCF2 mutations), and all had experienced at least 1 infectious episode (IQR 1–3)." (PMID 33168948, 2020). "Pattern "MTB" includes 177 genes whose expression levels changed specifically in response to infection with mycobacteria (e.g. NCF2, TNFSF13, CSF1)." (PMID 26586179, 2015). "We have reported previously that Ity3 influences ROS production during infection and this effect was mapped recently to a small sub-region named Ity3.1, which harbors the gene Ncf2, a subunit of the NADPH complex." (PMID 25161653, 2014). "To further characterize the downstream impact of Ity3.1 and Ncf2 on gene expression, we analyzed the data by evaluating variation in gene expression between Ity3, Ity3.RecG, or Ity3.RecN, and the control strain Ity at day 0 and day 3 post-infection." (PMID 25161653, 2014). "At a later stage of infection, the profound effect on host immunity was obvious as subunits of NADPH oxidase (CYBA, NCF2) required for pathogen clearance by phagocytes were enhanced." (PMID 35215144, 2022). "Notably, the levels of activated caspase-1 and released IL-1β in response to LPS and ATP, which activate the NLRP3 inflammasome; dsDNA transfection and infection with F. novicida, both as activators of the AIM2 inflammasome, were reduced following transfection with Ncf1, Ncf2, or Ncf4 siRNAs." (PMID 38886341, 2024).
tumor (18 papers, 2015 to 2026). "Through immunohistochemical staining, we found that the proteins encoded by GPR84 and NCF2 were significantly increased in tumor core, further suggesting a pro-tumoral role of these genes." (PMID 36177003, 2022). "Survival analysis of these genes in tumour samples identified seven genes that were associated with prognosis, including ACSL5, HSD17B11, CCL5, NCF2, PSME1, ACTB, and CYBB." (PMID 40299520, 2025). "Tumor biopsies obtained during surgery were analyzed for expression of NCF2, CYBB, CD68, CD163, and NCAM1 by RT-PCR." (PMID 38598844, 2024). "Secondly, we just implemented IHC to testify the prognostic role of NCF2 in HCC, while no experimental research was conducted to determine the mechanism by which NCF2 influences anti‐tumor immunity and the survival of HCC patients." (PMID 36680322, 2023). "As a result, GPR84, NCF2, HK3, LILRB2, and CCL18 significantly affected the overall survival (OS) of GBM patients (multivatiate Cox p < 0.05), of which the protein level of GPR84 and NCF2 was significantly increased in the tumor core region." (PMID 36177003, 2022). "Recent research published in the Journal of Pathology showed that genetic depletion of any of the NOX2 subunits Cyba, Cybb, Ncf1, Ncf2 and Ncf4 reduced the formation of lung metastases following intravenous injection of murine tumor cells." (PMID 30270440, 2019). "For example, NOX4 senses oxygen, produces ROS and is associated with tumor growth, and NOX5 and NCF2 produce superoxide." (PMID 26590118, 2016). "While 15 genes were found to be altered in two or more tumors, only 5 mutations occurred in more than one tumor model (ADCY2 p.V147L, ERBB2 p.I655V, NCF2 p.H308Q, SYNE1 p.L885V, and ZNF814 p.158V)." (PMID 26270481, 2015). "The protein encoded by NCF2 is a component of NADPH oxidase, which is involved in the regulation of cellular oxidative stress, immune responses, and inflammatory responses in the tumor microenvironment." (PMID 41197401, 2025). "In the last part of our study, we found that NCF2highM2high group potentially showed lower OS rate, which illustrated the relationship between NCF2 expression and M2 macrophages infiltration from another prospective, and implied the role of NCF2 in the regulation of anti‐tumor immunity." (PMID 36680322, 2023). "Among these significant genes of IL-4 signaling are CFLAR, ALOX5, PMAIP1, EGR1, NCF2, SLC39A8, and PEG10 which have been reported to be associated with tumor progression or chemotherapy-drug resistance through effecting proliferation and apoptosis in previous studies." (PMID 33506057, 2021). "In a recent contribution to The Journal of Pathology, van der Weyden et al2 reported that mice deficient in any of the five NOX2 subunits Cyba, Cybb, Ncf1, Ncf2 or Ncf4 were markedly less prone to develop lung metastases following intravenous injection of several histiotypes of tumor cells." (PMID 30270440, 2019). "Hence, NCF2 may function as an immune molecule to regulate anti‐tumor immunity and influence the prognosis of cancer patients." (PMID 36680322, 2023). "And a hub gene, NCF2, was identified as an independent prognostic factor of HCC patients as well as a potential factor to modulate the tumor microenvironment (TME) in HCC via regulating the polarization of macrophages." (PMID 36680322, 2023). "In order to preliminarily evaluate the role in tumorigenesis, we analyzed the different expression levels for NCF1, NCF2, and NCF4 between tumor and adjacent normal tissues in all TCGA tumors." (PMID 34708124, 2021). "Differential expression was observed between tumor and normal tissues for NCF1, NCF2, and NCF4 in KIRC data from TCGA." (PMID 34708124, 2021). "Gene expression difference analysis manifested that NCF2 was differentially expressed in normal and tumor tissue, rather than ITGB6 and PLAUR." (PMID 36680322, 2023).
tumor (continued). "Interestingly, the expression of NCF4 and NCF1, but not that of NCF2, was significantly downregulated in tumor tissues compared to that in control tissues." (PMID 38886341, 2024).
cancer (16 papers, 2019 to 2025). A tumor composed of atypical neoplastic, often pleomorphic cells that invade other tissues. "NCF2 is abnormally expressed in various cancers and is linked to macrophage infiltration and transformation in the TME." (PMID 40299520, 2025). "The role of NCF2 in the prognosis of cancer patients has previously been investigated by researchers." (PMID 36680322, 2023). "CYBB, CYBA, NCF1, NCF2, and RAC2 are NADPH oxidase (NOX) subunit genes and are associated with inflammation and fibrosis in multiple organs, such as the liver, lungs, and kidneys, as well as with various types of cancer." (PMID 37109526, 2023). "The other two genes, NCF2 and IFI30, play roles in immune response, antigen presentation, inflammation, cell invasion, and cell survival, and they have been considered as diagnostic and prognostic biomarkers in several cancers." (PMID 37685875, 2023). "Furthermore, we displayed the H3K27ac signals on the neutrophil cytosolic factor 2 (NCF2) gene locus by IGV in the eight selected malignant tumor cell lines, as representative; and we found that H3K27ac signals were highly enriched in the enhancer regions." (PMID 34722892, 2021). "The NCF2 gene was selected and IGV was used to show the H3K27ac signal on the enhancer of eight common malignant tumors." (PMID 34722892, 2021). "For instance, MAP3K8, MAP3K13, NCF2, NF-κB (family), NFATC2, NF-κB (complex), and NR2F2 were significantly disturbed by myricetin treatment, which are belonging to cancer related MAPK/NF-κB inflammatory signaling pathway." (PMID 30956980, 2019).
cardiovascular diseases (4 papers, 2015 to 2023). "The change in the NCF2 expression level significantly affects the level of reactive oxygen species (ROS), which is related to the occurrence and progression of cardiovascular diseases." (PMID 36602538, 2023).
immune disorder (3 papers, 2018 to 2023). "Additionally, due to genetic variants, deletions of NCF1, NCF2, and CYBB can cause hereditary immune diseases." (PMID 36718447, 2023).
bacterial infections (1 paper, 2023). "As NCF2 is necessary for NADPH oxidase, our data suggested that reprogrammed neutrophils in COVID‐19 have limited ability to produce ROS,39, 40, 46, 47, 48, 49, 50, 51, 52 perhaps increasing patient susceptibility to secondary bacterial infections." (PMID 36537107, 2023).
vasculopathy (1 paper, 2025). "More importantly, we constructed an AS mouse model by feeding ApoE−/− mice with a high‐fat diet and found that Ecd treatment alleviated vasculopathy and arterial ferroptosis and inhibited the secretion of inflammatory factors in vivo, which could be reversed by overexpression of NCF2." (PMID 40045169, 2025).
NCF2 also shares sentences with these, for which no sentence is quoted: psoriasis (3 papers); tuberculosis (3); Alzheimer disease (2); amyotrophic lateral sclerosis (2); cardiac hypertrophy (2); colitis (2); Crohn disease (2); diabetic cardiomyopathy (2); fungal infections (2); heart failure (2); hepatocellular carcinoma (2); inflammatory bowel disease (2); ischemia (2); ischemic stroke (2); melanoma (2); pneumonia (2); rectal cancer (2); type 2 diabetes mellitus (2); acute kidney injury (1); acute pancreatitis (1); adenocarcinoma (1); atrial fibrillation (1); autoimmune encephalitis (1); autosomal recessive chronic granulomatous disease (1); autosomal recessive HIES (1); cardiac interstitial fibrosis (1); Cerebral ischemia (1); cervical lymphadenitis (1); cervix (1); chronic multifocal osteomyelitis (1).
A further 42 diseases each share a sentence with NCF2 in 1 paper.